FAP (fibroblast activation protein alpha)
Diseases named in the same sentence as FAP in open-access papers (continued):
Sharing a sentence is not in itself a finding about the gene and the disease.
tumor (continued). "Collectively, these data indicate that FAP expression delineates a tumor microenvironment that is both pro-invasive and treatment-refractory." (PMID 41303595, 2025). "Considering the promising imaging results obtained with [89Zr]Zr-DFO-AMS002-1-FC, the research team decided to explore the therapeutic efficacy of [177Lu]Lu-DOTA-AMS002-1-FC in mice bearing FAP+ HT1080 tumor xenografts." (PMID 40542914, 2025). "Following the same protocol as our previous studies, FAP was considered positive when strong cytoplasmic immunostaining was detected in tumor interstitial cells previously identified as CAFs in H&E sections." (PMID 41303595, 2025). "This suggests that IL-15 secretion by FAP/IL-15 CAR-T cells is efficient, stable, and capable of overcoming uneven drug distribution caused by the tumor-stromal barrier." (PMID 41455698, 2025). "The survival time of tumor-bearing mice treated with 60 MBq of 177Lu-FAP-2286 was significantly extended." (PMID 40438601, 2025). "The limited expression of FAP in normal tissues and its pronounced overexpression in the tumor micro-environment makes it an interesting candidate for both diagnostic and therapeutic strategies." (PMID 41463267, 2025). "Key parameters were optimized in FAP-positive U87MG tumor-bearing mice, including the injected mass of 4AH29-TCO (200 μg) and the lag time (8 h) between the injections of 4AH29-TCO and [177Lu]Lu-DOTA-PEG7-tetrazine." (PMID 40131608, 2025). "Among these markers, α-SMA and FAP have been known as the specific markers for myofibroblasts, and their high expression often indicates a poor tumor prognosis." (PMID 40626005, 2025). "FAP +ve CAFs in OSCC can promote tumour cell invasion into the surrounding lymph nodes through CCL2, IL6 and CXCL8 secretion inducing M2-macrophage polarisation." (PMID 40379112, 2025). "Gallium-68-labeled fibroblast activation protein (FAP) inhibitor ([68Ga]Ga-FAPI-04) have attracted attention as promising radiotracers since 2019 owing to their superior ability to bind to FAP in the tumor stroma." (PMID 41268551, 2025). "Prodrugs conjugated to FAP substrates significantly reduced tumor growth and drug toxicity to organs." (PMID 40607439, 2025). "FAP is a cell surface glycoprotein predominantly expressed on activated fibroblasts within tumor tissues, particularly in CAFs." (PMID 40244052, 2025). "Previous studies of solid tumors have reported a correlation between FAP overexpression (particularly expression in tumor cells) and dismal prognosis." (PMID 41373408, 2025). "For instance, in pancreatic cancer, FAP-expressing CAFs can degrade extracellular matrix components such as collagen, opening a pathway for tumor cell metastasis." (PMID 40094065, 2025). "177Lu-FAP-2286 exhibited improved tumor uptake and biodistribution in HEK-FAP tumor-bearing mice, significantly prolonging the retention time in cancer compared to 177Lu-FAPI-46." (PMID 40438601, 2025). "FAP-targeted chimeric antigen receptor (CAR) T cells have shown promise in preclinical models by remodeling the tumor stroma and enhancing immune responses, with early clinical trials indicating acceptable safety." (PMID 41441395, 2025). "Fibroblast activation protein (FAP) is markedly overexpressed within the tumor stroma of a wide range of malignancies, representing a potential target for both molecular imaging and therapeutic intervention." (PMID 41425958, 2025). "This showed that universal (PI16+) fibroblasts from tumours show evidence of activation and inflammatory changes (including expression of FAP, COL1A1, IGF1)." (PMID 39757146, 2025). "FAP, as a specific biomarker of CAFs, is among the most promising tumor imaging markers, including PET, fluorescence, and multimodal molecular imaging targeting FAP." (PMID 40656546, 2025). "This trend matched the rise in fluorescent signal in the optical biodistribution study and resulted in decreased FAP(+)-tumor-to-liver ratio." (PMID 41258458, 2025).
tumor (continued). "In preclinical HEK-FAP mouse models, [177Lu]Lu-FAP-2286 demonstrated prolonged tumor retention time (≥ 72 h) compared to FAPI-46 (24 h) after injection." (PMID 41425958, 2025). "The Cox regression model revealed that densities of both FAP + CAFs, T-cyts, T-regs, and macrophages over the P75 at the tumor core were independent prognostic factors for worse CSS (p = 0.035)." (PMID 39751643, 2025). "Collectively, these findings support the conclusion that adoptive transfer of FAP/IL-15 CAR-T cells effectively inhibits tumor growth by concurrently promoting apoptosis and restraining both angiogenic activity and tumor cell proliferation." (PMID 41455698, 2025). "In a 2014 study, the FAP-activated prodrug ERGETGP-S12ADT effectively suppressed tumor growth in mouse xenograft models of human breast and prostate cancers with efficacy comparable to docetaxel but markedly lower systemic toxicity." (PMID 41441395, 2025). "This study reinforces the clinical significance of FAP expression in the tumor stroma of advanced ccRCC." (PMID 41303595, 2025). "FAP-overexpressing fibroblasts contribute to the generation of a tumor microenvironment that enhances tumor growth and invasiveness." (PMID 39895413, 2025). "The mechanisms by which FAP-positive CAFs aid cancer progression by promoting immunosuppression, tumor growth, metastasis, and drug-resistance are slowly being elucidated." (PMID 39868181, 2025). "These prodrugs, which remain inactive until cleaved by FAP upon systemic delivery, have induced tumor lysis and growth inhibition when injected intratumorally in human breast and prostate cancer xenografts." (PMID 40313969, 2025). "Compared with other tumor biomarker-targeted radiopharmaceuticals, the pan-tumoral expression of FAP makes FAPI applicable to the RLT of a wide range of tumors." (PMID 40438601, 2025). "FAP inhibitors work by suppressing the activity of FAP, thereby reducing the pro-tumor effects of CAFs and enhancing the sensitivity of tumors to chemotherapy and immunotherapy." (PMID 40909292, 2025). "Conversely, SPP1+ macrophages in CRC can promote immune evasion and tumor progression by supporting a desmoplastic tumor structure through interactions with FAP+ fibroblasts." (PMID 41361894, 2025). "MP0317, on the other hand, activates CD40+ APCs via its anti-FAP arm, which recognizes fibroblasts in the tumor microenvironment, therefore limiting toxicity to fibroblast-rich tumors." (PMID 40700292, 2025). "The Spearman correlation coefficient was used to evaluate the correlation between tumor uptake and the expression of FAP and αvβ3." (PMID 40365277, 2025). "FAP inhibitors (FAPIs) based on quinoline, as a novel strategy targeting the tumor stroma, have been developed as radiopharmaceuticals." (PMID 40485724, 2025). "In CCA specifically, immunohistochemical studies identified high expression of FAP in tumour stroma, strengthening the rationale for FAPI imaging in these patients." (PMID 41394868, 2025). "Emerging therapeutic strategies aim to selectively target tumor-promoting CAFs by exploiting fibroblast activation protein (FAP) or other specific markers to alleviate tumor-induced immunosuppression within the TME." (PMID 40497049, 2025). "Compared to ADCs, SqCCs demonstrated significantly higher median SUVmax (14.9 vs. 12.8, p = 0.031), FAPI-avid tumor volume (26.9 vs. 4.5, p < 0.001), and total lesion FAP expression (222.8 vs. 30.1, p < 0.001)." (PMID 40805245, 2025). "Fibroblast activation protein (FAP), a surface marker broadly expressed by CAFs in epithelial tumors, is a strong predictor of tumor invasiveness." (PMID 40963620, 2025). "Further immunohistochemical analysis showed that the CAF markers FAP and α-SMA exhibited significantly higher expression in C4-2B tumor tissues than in LNCaP tumors (FAP: p = 0.0047, α-SMA: p = 0.0262)." (PMID 40735647, 2025).
tumor (continued). "The lead candidate Nb159 was engineered for site-specific radiolabeling with 89Zr for PET imaging and with 177Lu coupled with PEG for therapeutic evaluation in mice bearing FAP-positive U87 tumor xenografts." (PMID 41460404, 2025). "This discrepancy suggests that FAP expression is influenced by both intrinsic and extrinsic factors, such as immune cell in-filtration, stromal components, and hypoxia in the tumor microenvironment." (PMID 41373408, 2025). "Perhaps one of the most promising radiopharmaceuticals for imaging is the fibroblast activation protein (FAP) inhibitor (FAPI), which targets cancer‐associated fibroblasts that are present in the tumour microenvironment." (PMID 40923371, 2025). "Since 2018, numerous FAP inhibitors (FAPIs) have been developed as tracers for tumor imaging via PET/computed tomography (CT), labelled with short half-life isotopes such as gallium-68 or fluorine-18." (PMID 40430477, 2025). "FAP was found to be significantly overexpressed in tumor tissues across all cancer types studied (P < 0.001), particularly within cancer-associated fibroblasts." (PMID 41244835, 2025). "Previous studies on melanoma have shown that FAP+ CAFs are enriched at the tumor edge, distributed closely to T cells, and inhibit T cell proliferation in a nitric oxide-dependent manner." (PMID 40855046, 2025). "As a member of the DPP4 family, FAP hydrolyzes peptide hormones and contributes to tumor progression by degrading the ECM, thereby promoting invasion and metastasis." (PMID 40656546, 2025). "Despite its variable expression among CAF subtypes and tumor stages, the high tumor-to-background contrast of FAP makes it a promising candidate for imaging and drug targeting." (PMID 41441395, 2025). "Analysis of the communication patterns of CAFs and TAMs also showed a coordinated tumor-promoting signaling communication model between FAP+ and MFAP5+ fibroblasts." (PMID 40438108, 2025). "In another first-in-human study in patients with advanced adenocarcinoma (pancreatic, breast, rectal, and ovarian), 177Lu-FAP-2286 showed prolonged tumor retention and high tumor absorbed doses, with low systemic exposure and manageable grade 3 adverse events." (PMID 41441395, 2025). "For instance, an adenoviral-vector vaccine designed to eliminate FAP+ cells reduced the number and suppressive function of immunosuppressive cells within tumours, concurrently inducing a robust CD8+ T cell response." (PMID 39780187, 2025). "Based on these findings, a subsequent study by the same group focused exclusively on SFT, where immunohistochemistry demonstrated FAP expression predominantly localized to tumor cell membranes." (PMID 41425958, 2025). "Our findings identify several tumor-specific interactions between FAP+ fibroblasts and TAMs, especially SPP1+ macrophages." (PMID 40438108, 2025). "Optimized FAP DNA vaccines further improved the anti-tumor effect by enhancing antigen secretion and immunogenicity." (PMID 40890855, 2025). "In the high-stiffness group, elevated expression of α-SMA and FAP was detected, predominantly distributed in the tumor stroma." (PMID 41502510, 2025). "FAP+ stromal cells have been shown to suppress anti-tumor immunity, and CXCL12 produced by FAP+ CAFs drives T cell exclusion and blunts responses to αCTLA-4/αPD-L1, findings that motivated later CXCR4-blockade combinations." (PMID 40940809, 2025). "In conclusion, we confirmed that the tumor tissue of intrathoracic SFTs, including SFTs of the pleura and pulmonary metastatic nodules from other organ-derived SFTs, expressed FAP." (PMID 40126602, 2025). "With the increased fraction of the FAP in the tumor microenvironment, reduced cytokine production was detected, indicating a lower interaction rate between T cells and cancer cells." (PMID 40704837, 2025).
tumor (continued). "Therapeutic outcomes in both systems demonstrated the benefits of simultaneous dual targeting of the tumor marker PSCA and the tumor microenvironment marker FAP, as reflected in the increased efficacy of cancer cell killing." (PMID 40704837, 2025). "The tumor stroma forms around malignant cells larger than 1–2 mm, providing the basis for targeted imaging using FAP." (PMID 40777126, 2025). "In recent years, fibroblast activation protein (FAP) has gained attention as a promising tumor target due to its widespread expression across various tumors." (PMID 40438601, 2025). "[89Zr]Zr-H15-Fc had the most rapid tumor localization, with uptake in FAP-expressing tumors being significantly greater than in negative tumors within 4 hours." (PMID 39868181, 2025). "Imaging contrasts and tumor-to-tissue ratios were consistent with the in vivo behavior of other radiolabeled anti-FAP mAbs; contrast and ratios improved as the radiopharmaceutical extravasated from the blood pool and began to localize in target tissues." (PMID 40542914, 2025). "Specifically, poor tumor retention remains a challenge for many FAP-targeted radiopharmaceuticals, hindering optimal therapeutic outcomes." (PMID 41460404, 2025). "FAP-positive CAFs contribute to tumor progression through ECM remodeling, immunosuppression, and angiogenesis, particularly in desmoplastic and therapy-resistant cancers." (PMID 41441395, 2025). "Univariate analysis demonstrated that FAP expression in CAFs was significantly associated with reduced DFS, consistent with its potential role in facilitating tumor recurrence." (PMID 41303595, 2025). "Combination therapy utilizing FAP-targeted RLT offers novel strategies to address drug resistance in tumor treatment." (PMID 40438601, 2025). "In a separate study, transfection of DCs with FAPα mRNA led to the antigen-specific activation of CD8+ T-cells, which were targeted towards the destruction of FAP-expressing CAFs within the tumor stroma." (PMID 40918451, 2025). "Selective FAP +ve CAF ablation in OAC in mouse models improved tumour cell response to 5-fluorouracil, suggesting a role of these stromal cells in therapy resistance." (PMID 40379112, 2025). "ST uncovered distinct distribution patterns of FAP+ CAF in the tumor bed, invasive margin, and peritumoral regions and identified 10 EcoCellTypes (ECTs) through unsupervised analysis." (PMID 40867511, 2025). "Analysis of 23,519 scRNA-seq data from 23 prostate samples revealed a pronounced accumulation of FAP+ fibroblasts in tumor tissues." (PMID 40438108, 2025). "This enables the selective elimination of FAP-positive tumor cells and CAFs in vitro and in vivo, disrupting pro-tumorigenic CAF functions, including angiogenesis." (PMID 41455698, 2025). "FAP-based PET imaging represents a significant advancement in oncologic and fibrotic disease imaging, offering superior tumor delineation, enhanced diagnostic accuracy, and the potential for targeted image-guided therapy." (PMID 40283957, 2025). "In pancreatic cancer, the coexistence of “tumor‐promoting” FAP+ CAFs and “tumor‐suppressing”α‐SMA+ CAFs highlights the complexity of CAF‐targeted therapies." (PMID 41164803, 2025). "FAP plays a significant role in remodeling the extracellular matrix, as well as in the proliferation and migration of tumor cells, thus promoting tumor growth and metastasis." (PMID 40094065, 2025). "The biological function of FAP in tumors remains incompletely understood, although most studies indicate that it plays a role in tumor progression through multiple mechanisms." (PMID 40438601, 2025). "Recent studies have demonstrated that the expression of FAPα in tumor cells enhances the activation of this signaling cascade." (PMID 40918451, 2025). "Talabostat, a small molecule dipeptidyl peptidase inhibitor of FAP, exhibited anti-tumour activity primarily through induction of tumour-specific cytotoxic T lymphocytes." (PMID 39780187, 2025).
tumor (continued). "Imaging: Given its high expression in CAFs and minimal presence in healthy tissues, FAP has emerged as a promising target for tumor imaging." (PMID 41441395, 2025). "The ability to selectively deliver payloads (such as radionuclides, cytostatics, or siRNA) into the cytoplasm of tumor cells is perhaps the most important difference to another popular theranostic target, fibroblast activation protein (FAP)." (PMID 40540027, 2025). "FAP-targeting ligands like PNT6555 deliver therapeutic agents directly to the tumor stroma by binding to FAP, increasing drug concentration and reducing side effects, offering both imaging and therapeutic functions." (PMID 39911388, 2025). "This specific localisation in both stroma and tumour cells makes FAP a promising prognostic and therapeutic target." (PMID 40741380, 2025). "The strong expression of FAP in tumor lesions (SUVmax of at least 10) suggests their suitability for FAP-RPT treatment." (PMID 39604653, 2025). "Previous study in the tumor tissues of metastatic non-small cell lung cancer (NSCLC) also demonstrated a significant enrichment of FAP+CAFs, with their abundance correlating with poor OS." (PMID 40843362, 2025). "In particular, there is a growing interest in co-targeting FAP with integrin αvβ3 for imaging of CAFs and tumor vasculature simultaneously." (PMID 40869454, 2025). "Several peptide-based FAP inhibitors (FAPI) with high affinities and selective binding to FAP-expressing tumours have been developed." (PMID 39780187, 2025). "In PDAC mouse models, depleting CAFs that express fibroblast activation protein (FAP) not only inhibits tumor growth alone but also potentiates the efficacy of anti-CTLA-4 and anti-PD-L1 ICB antibodies." (PMID 40723238, 2025). "In fibroblasts from NCL tissues, FAP is expressed at low levels, whereas in CAFs from tumour tissue high levels of FAP expression can be identified (this has been shown and discussed in our previous study)." (PMID 40640541, 2025). "The expression level of IL-31 in serum was measured by ELISA, while the abundance of FAP+CAFs in tumor tissues was assessed via IHC." (PMID 40843362, 2025). "These liposomes, which target both fibroblast activation protein (FAP) and endoglin, facilitate enhanced tumor detection and selective drug delivery." (PMID 39911388, 2025). "FAP influences tumor growth through multiple mechanisms, including promoting proliferation, invasion, angiogenesis, epithelial-mesenchymal transition (EMT), stem cell promotion, immune suppression, and drug resistance." (PMID 40607439, 2025). "Previous studies in lung cancer and pancreatic cancer also proved that targeting FAP-expressing CAFs can enhance anti-tumor immunity." (PMID 39870619, 2025). "MyCAFs, characterized by high expression of α-smooth muscle actin (α-SMA) and fibroblast activation protein alpha (FAP), drive desmoplastic stromal remodeling, which enhances tumor stiffness and restricts immune cell infiltration." (PMID 41438763, 2025). "These advanced constructs demonstrate how antibody formats can be engineered to overcome the limitations of early monotherapies, offering targeted cytotoxicity and immune activation by leveraging the tumor-restricted expression of FAP." (PMID 41441395, 2025). "Fibroblast activation protein (FAP) is prominently involved in the tumour microenvironment and tissue remodelling processes in most cancers, and its expression is also noted in normal skeletal muscle." (PMID 39956945, 2025). "Immunofluorescence indicated that TBP3743 tumors express mouse fibroblast activation protein (FAP), and prior work suggests favorable tumor-to-background albumin uptake over 48 h." (PMID 39753366, 2025). "DC vaccines transfected with FAP mRNA exhibited tumor-inhibiting effects in multiple tumor models, while composite DC vaccines can induce broad T cell responses and greater antitumor activity." (PMID 40890855, 2025).